GNRHR (gonadotropin releasing hormone receptor)
Diseases named in the same sentence as GNRHR in open-access papers (continued):
Sharing a sentence is not in itself a finding about the gene and the disease.
Alzheimer disease (18 papers, 2014 to 2025). A progressive, neurodegenerative disease characterized by loss of function and death of nerve cells in several areas of the brain leading to loss of cognitive function such as memory and language. "The four overrepresented pathways included the TGF-β signaling pathway, Gonadotropin-releasing hormone receptor pathway, Alzheimer disease presenilin pathway, and the Cadherin signaling pathway." (PMID 40763299, 2025). "Recently, it has been reported that GV1001 is a novel ligand for the gonadotropin-releasing hormone receptor (GnRHR) by selectively stimulating the Gαs/cAMP pathway, suggesting the possibility of a treatment for Alzheimer’s disease as well as cancer." (PMID 39062525, 2024). "These included the TGF-β signaling pathway (raw p=5.8×10−6), Alzheimer disease presenilin pathway (p=5.8×10−5), Gonadotropin-releasing hormone receptor pathway (p=4.8×10−5), and the Cadherin signaling pathway (p=4.8×10−3)." (PMID 39763728, 2024). "Further pathways like the gonadotropin-releasing hormone receptor pathway or the Alzheimer disease-amyloid secretase pathway were statistically significantly affected by downregulated DTGs at day 120 pi." (PMID 35056627, 2022). "The Panther Pathway enrichment analysis retrieved five significant pathways: blood coagulation, integrin signaling, Alzheimer disease-presenilin, angiogenesis and gonadotropin-releasing hormone receptor pathways." (PMID 33827428, 2021). "Pathways commonly identified in resected tissues (integrin signaling, inflammation, gonadotropin releasing hormone receptor, Alzheimer disease-presenilin and plasminogen activating cascade) were also frequently found in the cell lines studied." (PMID 26279647, 2015). "Seven major pathways were identified, including FGF, Integrin, Wnt, and Cadherin signalling pathways, as well as Angiogenesis, Gonadotropin-releasing hormone receptor, and the Alzheimer disease-presenilin pathway, with all seven pathways being implicated in lung cancer." (PMID 35595947, 2022). "Annotated genes in the TGF-β signaling (TGF-β) pathway and Gonadotropin-releasing hormone receptor (GRHR) pathways are highly overlapped, as are genes in the Cadherin signaling (CADH) and Alzheimer’s disease presenilin(ALZ) pathways." (PMID 39763728, 2024). "The pathways overexpressed by the low MWM performance group included inflammation mediated by chemokine and cytokine signaling pathway, the gonadotropin releasing hormone receptor pathway, wnt signaling pathway, integrin signaling pathway, PDGF signaling pathway, and Alzheimer's disease." (PMID 28912681, 2017).
endometriosis (16 papers, 2015 to 2025). The growth of functional endometrial tissue in anatomic sites outside the uterine body. "Elagolix sodium salt is the first marketed orally active non-peptide gonadotropin-releasing hormone receptor antagonist (GnRHR-ant) for the management of hormone dependent diseases, such as endometriosis and uterine fibroids." (PMID 37175271, 2023). "GnRHR expression was observed in 100% (6/6) of endometria (EM), 88.9% (40/45) of ovarian endometrioma (OE), and 88.4% (15/17) of deep endometriosis (DIE) samples by IHC analysis." (PMID 38089464, 2023). "Gonadotropin-releasing hormone receptor (GnRHR) expression was detected in endometriosis tissues and cell lines via immunohistochemistry and western blotting." (PMID 38089464, 2023). "The expression of GnRHR was detected in endometriosis tissues and cell lines to evaluate the feasibility of GnRHR as an imaging target for endometriosis, and subsequently, the binding capacities of GnRHa, GnRHa-ICG, and ICG were determined in vitro and in vivo." (PMID 38089464, 2023). "The dysregulation of the gonadotropin-releasing hormone receptor pathway may result in high secretion of estrogen, a characteristic of patients with endometriosis." (PMID 31169291, 2019). "Moreover, high expression of GnRHR has been reported in endometriotic cells and tissues, which is consistent with our results showing a nearly 90% expression rate in both ovarian endometrioma and deep infiltrating endometriosis." (PMID 38089464, 2023). "Hence, GnRHR is a promising imaging target in endometriosis." (PMID 38089464, 2023). "Gonadotropin-releasing hormone receptor pathway, inflammation mediated by chemokine and cytokine signaling, the CCKR signaling pathway, angiogenesis and the integrin signaling pathway were found to be the most represented pathway among genes associated with endometriosis." (PMID 31169291, 2019).
hypogonadotropic hypogonadism (16 papers, 2012 to 2023). Abnormal ovarian or testicular function due to insufficient hormonal stimulation from the hypothalamic-pituitary axis. "Such mutations in the GNRHR are linked to normosmic hypogonadotropic hypogonadism and lead to various clinical symptoms, including delayed puberty, infertility, and impaired sexual development." (PMID 37958948, 2023). "The main feature in patients carrying mutations in GnRHR is normosmic hypogonadotropic hypogonadism." (PMID 37958948, 2023). "The properties of pharmacoperone IN3 were further studied in transgenic mice with a hypogonadotropic hypogonadism phenotype due to the GnRHR p.Glu90Lys mutation." (PMID 37958948, 2023). "The pathogenic GNRHR variant c.317A>G (p.Gln106Arg) was found in another male subject; also this variant has been reported in association with hypogonadotropic hypogonadism." (PMID 33401665, 2021). "We reported a novel GNRHR mutation in a pedigree with congenital idiopathic hypogonadotropic hypogonadism." (PMID 33592857, 2021). "Biallelic, partial loss-of-function mutations in GNRHR cause a wide spectrum of reproductive phenotypes from constitutional delay of growth and puberty to complete congenital hypogonadotropic hypogonadism." (PMID 29182666, 2017). "To date, at least 20 additional mutations in GNRHR have been identified in patients with sporadic and familial isolated hypogonadotropic hypogonadism." (PMID 23248618, 2012). "Two separate groups initially reported loss-of-function mutations in the GNRHR gene in patients with isolated hypogonadotropic hypogonadism." (PMID 23248618, 2012). "The GNRHR gene is related to hypogonadotropic hypogonadism, encoding the GnRH receptor." (PMID 33592857, 2021). "Cloning of the human GNRHR cDNA has led to the identification of mutations in the coding sequence that are associated with variable clinical features ranging from partial to complete hypogonadotropic hypogonadism." (PMID 23248618, 2012). "For example, the sequence of the gonadotropin-releasing hormone receptor (GnRHR) has been deeply mapped, since even a single mutation can lead to its inefficient localization on the plasma membrane, a condition that has been linked to congenital isolated hypogonadotropic hypogonadism." (PMID 35159337, 2022). "A discussion on tissue expression patterns of GNRHR, extending beyond the pituitary gland, and their possible implication on clinical entities such as hypogonadotropic hypogonadism is also presented." (PMID 37958948, 2023). "For instance, these regions contain the gonadotropin releasing hormone receptor (GNRHR) and gonadotropin releasing hormone 1 (GNRH1) genes, both of which are associated with hypogonadotropic hypogonadism and play an important role in reproduction." (PMID 29790964, 2018). "A 17-year-old male patient with isolated hypogonadotropic hypogonadism caused by a GnRH receptor (GNRHR) mutation had no pubertal development and a BA of 14.5 years, and his 16-year-old sister with the same mutation had no thelarche and a BA of 12.5 years." (PMID 36072933, 2022).
endometrial cancer (13 papers, 2009 to 2025). Primary or metastatic malignant neoplasm involving the endometrium (mucous membrane that lines the endometrial cavity). "The role of pituitary gonadotropin-releasing hormone receptors (GnRH-R), involved in G-protein-coupled receptors (GPCRs) mediated intracellular signaling pathway, are proven to be crucial in various cancers, such as endometrial cancer." (PMID 35893039, 2022). "Triptorelin, cetrorelix (pan GnRHR antagonist), and GnRH2 exerted anti-proliferative effects on endometrial cancer cells (Ishikawa, HEC-1A, and HEC-1B) that produce GnRHR1 and GnRHR2 transcripts." (PMID 38260130, 2023).
Obesity (10 papers, 2014 to 2026). Accumulation of substantial excess body fat. "We conclude that phoenixin possesses a significant role in the positive modulation of obesity-induced fertility impairment by acting locally on mitochondrial machinery and GnRHR gene upregulation together with its well-known central effect." (PMID 35972578, 2022). "Here, we explored whether the gonadotropin-releasing hormone receptor (GnRHR) was expressed in adipocytes and how GnRHR mediated lipid accumulation and the development of obesity." (PMID 36035370, 2022). "It has been demonstrated that adiponectin might provide a link between obesity and abnormal reproductive functioning by decreasing luteinizing hormone (LH) secretion and inhibiting GnRH receptor (GnRHR) mRNA expression in the pituitary." (PMID 25505448, 2014). "Monogenic forms, such as hemizygous ANOS1 mutations or biallelic GnRHR or PROKR2 variants, can explain the more severe phenotypes whereas various combinations of minor IHH alleles with or without acquired factors, such as obesity, can justify the adult-onset of IHH." (PMID 30669598, 2019).
Anosmia (9 papers, 2011 to 2025). An inability to perceive odors. "Among the affected members was F1, a 65-year-old female carrier of both theANOS1 and GNRHR mutations, who exhibited nosymptoms of hypogonadism or anosmia." (PMID 41165467, 2025). "P/LP variants were detected in patients presenting with anosmia/hyposmia in genes previously reported for nIHH (GNRHR) or SOD/CPHD (LHX4, SOX3)." (PMID 34198905, 2021). "Autosomal recessive mutations in GNRHR typically result inisolated hypogonadotropic hypogonadism without anosmia, contributing to thephenotypic variability seen in CHH." (PMID 41165467, 2025). "Loss-of-function variants of the gonadotropin-releasing hormone receptor (GNRHR) are associated with CHH without anosmia." (PMID 36371229, 2022). "Loss-of-function variants of the GNRHR are associated with CHH without anosmia." (PMID 36371229, 2022). "Perhaps a specific sort of defect in GNRHR, LHX4, or SOX3 can result in a complete clinical picture of Kallmann syndrome with smell disturbances." (PMID 34198905, 2021).
melanoma (9 papers, 2018 to 2025). A malignant, usually aggressive tumor composed of atypical, neoplastic melanocytes. "Previous studies have shown that the gonadotropin-releasing hormone receptor pathway is not only a cancer cell autocrine regulatory factor but is also expressed in hormone-independent melanoma, which can negatively regulate the proliferation and metastasis of melanoma cells." (PMID 33313406, 2020). "The gonadotropin-releasing hormone receptors (GnRH-R) overexpressed on different tumors (e.g., melanoma) could be utilized for drug-targeting by application of a GnRH analog as a carrier to deliver a covalently linked chemotherapeutic drug directly to the tumor cells." (PMID 30344773, 2018). "GnRHR expression extends beyond the pituitary gland, and is found in reproductive tissues such as ovaries, uterus, and prostate and non-reproductive tissues such as heart, muscles, liver and melanoma cells." (PMID 37958948, 2023).
Infertility (7 papers, 2016 to 2025). "Emerging evidence suggests that immune-mediated mechanisms targeting FSH, its receptor, gonadotropin-releasing hormone receptor (GnRHR), and ovarian antigens may play a role in ovarian dysfunction, hyperandrogenism, and infertility associated with PCOS." (PMID 40362363, 2025). "Given its importance in reproductive regulation, the GnRHR has emerged as a potential target for the treatment of infertility and sex steroid-dependent hyperplasia, such as uterine fibroids, endometriosis, and prostate cancer." (PMID 37958948, 2023). "Enhanced GnRH secretion and increased pituitary GnRHR concentrations facilitate ovulation in mammals, whereas the absence of GnRHR may inhibit ovulation, potentially leading to infertility." (PMID 39795025, 2025). "In this study, the GnRH1, GnRHR, KISS1, KISS1R, TAC3 and TAC3R genes were analyzed in two unrelated nIHH patients successfully treated for infertility." (PMID 27544332, 2016). "In contrast, cetrorelix did not reduce the GnRHR-AAb activity in IgG from controls with ovulatory infertility, suggesting a lack of significant autoimmune activation of the receptor in this group." (PMID 40362363, 2025).
pancreatic cancer (7 papers, 2010 to 2025). "Based on the Bittner multi-cancer dataset, GnRH and GnRHR were upregulated in pancreatic cancer." (PMID 31263453, 2019).
congenital hypogonadotropic hypogonadism (6 papers, 2016 to 2025). Congenital hypogonadotropic hypogonadism (CHH) is a rare disorder of sexual maturation characterized by gonadotropin (Gn) deficiency with low sex steroid levels associated with low levels of follicle stimulating hormone (FSH) and luteinizing hormone (LH). "Reproduction development is disrupted somewhat by dysfunction of the GnRHR including causative mutations in the GnRHR gene resulting in the delay of puberty and congenital hypogonadotropic hypogonadism (CHH)." (PMID 37958948, 2023). "This approach holds promise for the treatment of genetic disorders caused by mutations in GNRHR, such as congenital hypogonadotropic hypogonadism (CHH)." (PMID 37958948, 2023). "Genes which are associated with congenital hypogonadotropic hypogonadism include : the Fibroblast Growth Factor receptor 1 gene (FGFR), prokineticin receptor 2 gene (PROKR2), GNRH receptor gene (GNRHR) and the Kallmann syndrome 1(KAL1) sequence gene (also known as ANOS-1)." (PMID 38062345, 2024). "Only rarely have mutations in genes known to cause aberrations of the hypothalamic-pituitary-gonadal axis been identified in cases of delayed puberty, and the majority of these are in relatives of patients with congenital hypogonadotropic hypogonadism (CHH), for example in the FGFR1 and GNRHR genes." (PMID 31293522, 2019).
hypogonadism (6 papers, 2012 to 2025). A disorder characterized by decreased function of the gonads. "Specifically, digenic combinations of mutations in theANOS1 and GNRHR genes were linked to moresevere phenotypes in the affected males, including compounded hypogonadism andanosmia." (PMID 41165467, 2025). "As with the GnRHR, mutations resulting in changes in protein sequence of gonadotropin receptors may lead to loss-of-function of the receptor, leading to hypogonadism in humans." (PMID 34830210, 2021). "The decrease in GnRHR status in the adenohypophysis of rats subjected to the HFD-HF diet leads to hypogonadotropism, which adversely affects ovarian follicular development, maturation, ovulation, and also steroidogenesis." (PMID 36359843, 2022). "In the present study, the HFD-HF diet decreased FSH and LH levels (hypogonadotropism), which may be due to the reduced GnRHR." (PMID 36359843, 2022). "In a long-term clinical follow-up, three unrelated subjects with digenic defects (proband 9: CHD7 p.N1030H and FGFR1 p.R285W; proband 10: CHD7 p.N1030H and FGFR1 p.R285W; and proband 25: GNRHR p.R139H, GNRHR p.N10_Q11delinsKK, and CHD7 p.K683_T684insAK) displayed a reversal of hypogonadism." (PMID 34198905, 2021).
lung carcinoma (6 papers, 2019 to 2025). "Since lung cancers have been less investigated in the context of GnRH targeting, we proved the high GnRHR expression of EBC-1 cells by western blot for the first time." (PMID 31717403, 2019).
Parkinson disease (6 papers, 2016 to 2025). A progressive degenerative disorder of the central nervous system characterized by loss of dopamine producing neurons in the substantia nigra and the presence of Lewy bodies in the substantia nigra and locus coeruleus. "Functional GO enrichment analysis again identified the gonadotropin-releasing hormone receptor pathway, as well as Parkinson’s disease and the Wnt signaling pathway, as dysregulated genes." (PMID 41228255, 2025). "The underexpressed proteins were annotated to fructose galactose metabolism, apoptosis signaling pathway, plasminogen activating cascade, Parkinson’s disease, gonadotropin releasing hormone receptor pathway, glycolysis and blood coagulation pathways." (PMID 26988818, 2016). "In addition, some atypical functions relating to immunity were indicated in the host, namely gonadotropin-releasing hormone receptor pathway, Parkinson’s disease, and circadian clock systems." (PMID 26881892, 2016). "In accordance with previous findings, these 83 cancer related proteins confirmed the overrepresentation of the FAS and the FGF signaling, the CCKR signaling map, the Parkinson’s disease, the EGF receptor signaling, the integrin signaling, and the gonadotropin-releasing hormone receptor pathways." (PMID 32183175, 2020).
Huntington disease (5 papers, 2017 to 2025). Huntington disease (HD) is a rare neurodegenerative disorder of the central nervous system characterized by unwanted choreatic movements, behavioral and psychiatric disturbances and dementia. "Kyoto Encyclopedia of Genes and Genomes (KEGG) analysis showed that differentially expressed miRNA target genes were mainly concentrated into the “gonadotropin-releasing hormone receptor pathway” and the “Huntington disease pathway”." (PMID 35936223, 2022). "For the downregulated genes, the pathways with more hits were angiogenesis, cadherin signaling, gonadotropin-releasing hormone receptor, Huntington's disease, inflammation mediated by chemokine and cytokine signaling, integrin signaling, Wnt β-catenin, and TGF-β signaling." (PMID 29213289, 2017). "For the downregulated genes, the pathways with the most hits were angiogenesis, cadherin signaling, gonadotropin-releasing hormone receptor, Huntington disease, inflammation mediated by chemokine and cytokine signaling, integrin signaling, and Wnt and TGF-beta signaling." (PMID 29213289, 2017).
leiomyoma (5 papers, 2016 to 2022). A well-circumscribed benign smooth muscle neoplasm characterized by the presence of spindle cells with cigar-shaped nuclei, interlacing fascicles, and a whorled pattern. "Recently, relugolix, an oral gonadotropin-releasing hormone receptor antagonist, has been considered an effective therapy for leiomyoma based on a phase 3 study in Japanese women." (PMID 34412607, 2021).
polycystic ovary syndrome (5 papers, 2021 to 2024). A disorder that manifests as multiple cysts on the ovaries. "A study on individuals with polycystic ovary syndrome does suggest that there are pathophysiological links between the GNRHR locus and thyroid function." (PMID 38196663, 2024). "This would support the concept that GnRHR‐AAb‐induced hyperandrogenemia may be a significant component for the induction of insulin resistance." (PMID 33356018, 2021). "In this study, we established an autoimmune rat model using a synthetic GnRHR ECL2 peptide to induce the production of GnRHR‐AAb and hyperandrogenemia." (PMID 33356018, 2021).